OR2AG1 (olfactory receptor family 2 subfamily AG member 1)
Description:
Odorant receptor.
Synonyms: OR2AG3; OR11-79
Tractability: Antibody: UniProt places it where antibodies can reach, with medium confidence; UniProt predicts a signal peptide or a membrane-spanning region; its Gene Ontology location is reachable by antibodies, with medium confidence.
Gene: Protein-coding gene on chromosome 11 (6,783,020 to 6,791,558, forward strand). Ensembl gene ENSG00000279486.
Subcellular location: Cell membrane
Pathways (Reactome):
Sensory Perception: Expression and translocation of olfactory receptors
Gene Ontology:
Molecular function: protein binding; olfactory receptor activity; G protein-coupled receptor activity
Biological process: detection of chemical stimulus involved in sensory perception of smell; G protein-coupled receptor signaling pathway
Cellular component: plasma membrane; membrane
Genetic constraint (gnomAD): Loss-of-function variants: 6 observed, 2.21 expected, observed/expected ratio (o/e) 2.71. That is too few expected variants to judge how well the gene tolerates losing a copy. Missense variants: 388 observed, 394.22 expected, observed/expected ratio (o/e) 0.98, 90% interval 0.9 to 1.07. Synonymous variants: 157 observed, 158.9 expected, observed/expected ratio (o/e) 0.99, 90% interval 0.87 to 1.13.
Homologues: Orthologues: chimpanzee OR2AG1 (98% identical), macaque OR2AG2 (88% identical), rat Or2ag1 (83% identical), mouse Or2ag1 (83% identical), dog OR2AG1C (82% identical), dog OR2AG1D (81% identical), dog OR2AG2 (81% identical), dog OR2AG2C (80% identical), mouse Or2ag2 (80% identical), mouse Or2ag2b (80% identical), mouse Or2ag18 (80% identical), mouse Or2ag1b (79% identical), and 17 more. Paralogues in human: OR2AG2 (87% identical), OR2T2 (49% identical), OR2T1 (48% identical), OR2T35 (48% identical), OR2T29 (47% identical), OR2T5 (47% identical), OR2T11 (47% identical), OR2T27 (47% identical), OR2M2 (47% identical), OR2T12 (47% identical), OR2T4 (47% identical), OR2M3 (46% identical), and 80 more.
Diseases named in the same sentence as OR2AG1 in open-access papers:
OR2AG1 is named in the same sentence as 6 diseases in open-access papers, as found by Europe PMC text mining. Sharing a sentence is not in itself a finding about the gene and the disease.
OR2AG1 shares sentences with these, for which no sentence is quoted: cervical cancer (2 papers); breast carcinoma (1); cancer (1); cataract (1); cerebral infarction (1); Pruritus (1).